ZNF518B (zinc finger protein 518B)
Description:
Through its association with the EHMT1-EHMT2/G9A and PRC2/EED-EZH2 histone methyltransferase complexes may function in gene silencing, regulating repressive post-translational methylation of histone tails at promoters of target genes.
Synonyms: KIAA1729
Tractability: PROTAC: UniProt records ubiquitination sites on it; ubiquitination databases record sites on it.
Gene: Protein-coding gene on chromosome 4 (10,439,873 to 10,461,381, reverse strand). Ensembl gene ENSG00000178163.
Subcellular location: Nucleus
Subcellular location (Human Protein Atlas): Nucleoplasm
Gene Ontology:
Molecular function: DNA-binding transcription factor activity, RNA polymerase II-specific
Biological process: regulation of transcription by RNA polymerase II
Cellular component: nucleus
Genetic constraint (gnomAD): Loss-of-function variants: 23 observed, 59.09 expected, observed/expected ratio (o/e) 0.39, 90% interval 0.28 to 0.55. The upper end of that interval is the gene's LOEUF score, 0.55, which puts it in group 2 of 6, group 1 being the genes least tolerant of losing a copy. Missense variants: 1,460 observed, 1,343 expected, observed/expected ratio (o/e) 1.09, 90% interval 1.04 to 1.13. Synonymous variants: 529 observed, 493.83 expected, observed/expected ratio (o/e) 1.07, 90% interval 1 to 1.15.
Homologues: Orthologues: chimpanzee ZNF518B (99% identical), macaque ZNF518B (96% identical), dog ZNF518B (80% identical), rabbit ZNF518B (80% identical), guinea pig ZNF518B (74% identical), mouse Zfp518b (72% identical), rat Zfp518b (71% identical), pig ZNF518B (70% identical), tropical clawed frog znf518b (18% identical), Drosophila melanogaster hb (8% identical), Caenorhabditis elegans Y5F2A.4 (4% identical), Caenorhabditis elegans hbl-1 (4% identical), and 1 more. Paralogues in human: ZNF518A (22% identical), PEG3 (9% identical), ZNF770 (7% identical), REST (6% identical), PLAGL2 (6% identical), PLAG1 (5% identical), PLAGL1 (5% identical), ZBTB35 (5% identical), ZSCAN5C (4% identical), ZSCAN5A (4% identical), OVOL1 (4% identical), ZSCAN5B (4% identical), and 17 more.
Diseases named in the same sentence as ZNF518B in open-access papers:
ZNF518B is named in the same sentence as 9 diseases in open-access papers, as found by Europe PMC text mining. Sharing a sentence is not in itself a finding about the gene and the disease. The quoted sentences say what the papers report.
colorectal cancer (2 papers, 2019 to 2021). A primary or metastatic malignant neoplasm that affects the colon or rectum. "As the dysregulation of this enzyme has been associated with CRC, we further developed the initial work with CRC cell lines and showed that ZNF518B is up-regulated in patients of colorectal cancer." (PMID 33801071, 2021). "The ZNF518B gene, which is up-regulated in colorectal cancer, plays a role in cell dissemination and metastasis." (PMID 33801071, 2021). "The ZNF518B gene, which is up-regulated in colorectal cancer, plays a role in metastasis, but neither the mechanisms involved in this process nor the role of the different isoforms of the gene are known." (PMID 33801071, 2021).
gout (2 papers, 2022 to 2023). A condition characterized by painful swelling of the joints, which is caused by deposition of urate crystals. "The involved genes were ABCG2, SLC2A9, PKD2, ZNF518B, ALDH2, HECTD4, and MAPKAPK5 in the phenotype of gout; and only gene SLC2A9 was found in the AH phenotype." (PMID 36221101, 2022).
breast carcinoma (1 paper, 2021). "Among the genes activated by ZNF518B, CERK is associated with highly aggressive human breast cancer and GINS1 expression correlates with proliferation of breast cancer cells and with poor prognosis in hepatocellular carcinoma." (PMID 33801071, 2021).
cancer (6 papers, 2019 to 2024). A tumor composed of atypical neoplastic, often pleomorphic cells that invade other tissues. "The distribution of the degree of methylation indicated that in the normal lung tissue group, ZNF518B and ZNF502 presented a hypomethylated state, while in the EAC cancer group, ZNF518B and ZNF502 presented a hypermethylated state." (PMID 34222478, 2021). "The study of the transcriptome of DLD1 and HCT116 cells revealed that many genes affected by silencing ZNF518B are related to cancer." (PMID 33801071, 2021). "These facts establish a potential relationship between ZNF518B and cancer, because a dysregulation of G9A has been found in several types of cancer." (PMID 31249328, 2019).
tumor (4 papers, 2013 to 2023). "The present research was undertaken with the aim of exploring the molecular mechanisms involved in the oncogenicity of ZNF518B, which has been shown to favour tumour cell dissemination in CRC." (PMID 33801071, 2021). "A second mechanism to account for the oncogenic behaviour of ZNF518B is that it represses tumour suppressor genes." (PMID 33801071, 2021). "The gene does not affect cell proliferation, but plays a significant role in cell migration and invasiveness and induces changes in the epithelial-to-mesenchymal transition markers, suggesting that ZNF518B favours tumour cell dissemination." (PMID 31249328, 2019). "Here, after analysing cDNA array containing 43 tumour and 5 normal mucosa samples, we report that the expression of the ZNF518B gene as a whole and that of its two major splicing isoforms are significantly increased in tumours." (PMID 31249328, 2019). "It has been proposed that overexpression of ZNF518B might have a role in tumor cell dissemination." (PMID 37917782, 2023). "Therefore, we reasoned that the oncogenicity of ZNF518B may be explained in part by its canonical protein binds, through its zinc-finger domains or control sequences of some tumour suppressor genes tethering any of the methyltransferases." (PMID 33801071, 2021). "The results described here, obtained from both a cDNA array of 43 tumour and 5 normal mucosa samples and from a local prospective cohort including 70 tumour and 69 adjacent non-tumour samples, show for the first time that the expression of ZNF518B may correlate with CRC." (PMID 31249328, 2019). "Our results show that the ZNF518B protein recruits the histone methyltransferases EZH2 and G9A on several tumour suppressor genes and the resulting repressive marks on histone H3 contribute to reducing the expression level of these genes." (PMID 33801071, 2021).
ZNF518B also shares sentences with these, for which no sentence is quoted: diabetes (1 paper); glioma (1); hepatocellular carcinoma (1); hyperuricemia (1).